CASP8 (caspase 8)
Diseases named in the same sentence as CASP8 in open-access papers (continued):
Sharing a sentence is not in itself a finding about the gene and the disease.
multiple myeloma (continued). "This compound caused mitotic arrest and apoptosis of myeloma cells characterized by cleavage of poly (ADP-ribose) polymerase-1 and caspase-8, as well as decreased protein expression of mcl-1." (PMID 27613836, 2016). "In an in vitro study, it has been demonstrated that oprozomib inhibits growth and migration of myeloma cell lines and induces apoptosis through the activation of caspase-8, caspase-9 and caspase-3 and poly(ADP) ribose polymerase (PARP)." (PMID 26579531, 2015). "It causes cell cycle arrest, anti-angiogenic effects, induction of the stress response and apoptosis of multiple myeloma cells mediated by caspase-8/9." (PMID 23420708, 2013). "Functional studies have identified upregulation of DR5 and activation of caspase-8 as key mechanisms by which PBOX-15 induces apoptosis in myeloma cells." (PMID 21179037, 2011). "Bortezomib activates caspase-8 in myeloma cells, thereby inducing apoptosis of myeloma cells." (PMID 35321428, 2022). "First, I introduce the caspase-8 signaling pathway in myeloma treatment." (PMID 35321428, 2022). "Bortezomib and lenalidomide activate caspase-8 and promote the apoptosis of myeloma cells." (PMID 35321428, 2022). "Finally, I discuss future perspectives on caspase-8-based therapy for myeloma.via cereblon IKZF1/3 cascade." (PMID 35321428, 2022). "However, we have previously shown that caspase-8 activation attenuates the anti-myeloma effect of bortezomib and lenalidomide." (PMID 35321428, 2022). "Using myeloma as a model system, we further demonstrated that blockage of the CRBN cleavage by pharmacological inhibition or genetic depletion of CASP-8 potentiates the anti-myeloma activity of Len in both myeloma cell lines and bone marrow primary myeloma cells." (PMID 33392195, 2020). "Therefore, combination of CASP-8 inhibitor with Len would most likely benefit to the treatment of myeloma, which was indeed confirmed in myeloma cell lines and primary myeloma cells." (PMID 33392195, 2020). "Nevertheless, CASP-8 inhibition enhances the anti-myeloma activity of Len in both cases." (PMID 33392195, 2020). "Using this discovery, we further disclosed that the anti-myeloma activity of IMiDs can be augmented by inhibiting the CASP-8 activation and suggests a potential new combination therapy that might benefit myeloma patients." (PMID 33392195, 2020). "To further validate whether CASP-8 modulates the anti-myeloma activity of Len in primary cells, we cultured CD138+ primary myeloma cells from bone marrow of two patients and treated them with CASP-8 inhibitor z-IETD-fmk and/or Len." (PMID 33392195, 2020). "In multiple myeloma cells, bortezomib has been shown to activate both the intrinsic apoptotic pathway, involving mitochondrial cytochrome c release and caspase-9, as well as the extrinsic, Fas/caspase-8-dependent apoptotic pathway." (PMID 23226303, 2012). "Moreover, it has been described that SN-38 induces Fas upregulation and caspase 8-mediated apoptosis in multiple myeloma cells." (PMID 18443598, 2008). "Furthermore, future directions of caspase-8-based therapy for myeloma have been discussed." (PMID 35321428, 2022). "However, caspase-8 inhibition potentiated the antiproliferative effect of lenalidomide and bortezomib in myeloma cells, suggesting that caspase-8 could regulate proliferation and apoptosis in the opposite pathway." (PMID 35321428, 2022). "Therefore, we thought to use myeloma cells as a model system to explore whether CASP-8 regulates CRBN levels after addition of Len." (PMID 33392195, 2020). "It should be noted that different myeloma cell lines and primary myeloma cells may have distinct genetic backgrounds, such as mutations and expression level of genes including CRBN, CASP-8, and DDB1, which affect cell proliferation and regulate cell death pathways." (PMID 33392195, 2020).
multiple myeloma (continued). "Therefore, a strategy could be an alternative treatment of myeloma with the combination of IMiDs and CASP-8 inhibitors, which suppresses the proliferation of myeloma cells." (PMID 33392195, 2020). "These phenomena suggest that CASP-8 inhibition might affect the proliferation of myeloma cells." (PMID 33392195, 2020). "However, the cleavage of CRBN can be induced by CASP-8 activation, which could be mediated by Len in myeloma cells, and the stability of the cleaved CRBN is reduced." (PMID 33392195, 2020). "Moreover, we delineate the mechanism of PBOX-15 activity in myeloma cells: we show induction of caspase-8-dependent apoptosis, independent activation of the extrinsic and intrinsic apoptotic pathways, and early downregulation of the proapoptotic BH3-only protein Bim." (PMID 21179037, 2011). "The result showed that those with lower CASP-8 mRNA levels exhibited a higher overall survival rate, suggesting that CASP-8 expression may be an important factor in determining the clinical response to Len-based therapies likely through the regulation of CRBN protein level in myeloma." (PMID 33392195, 2020). "Nevertheless, both mechanisms support the idea that inhibiting CASP-8 activity increases CRBN protein level and benefits to the therapeutic effect of Len for the treatment of myeloma." (PMID 33392195, 2020). "In combination with CASP-8 inhibitor, Len further elevates the CRBN protein level, resulting in the enhanced degradation of IKZF1 and IKZF3 and enhanced anti-myeloma activity." (PMID 33392195, 2020). "The present study discovered that the stability of the substrate receptor of an E3 ligase can be modulated by CASP-8 and suggested that administration of CASP-8 inhibitors enhances the overall effectiveness of Len-based combination therapy in myeloma." (PMID 33392195, 2020). "Decursin enhanced caspase-9-mediated apoptosis in doxorubicin-treated multiple myeloma cells, via the mTOR and STAT3 pathways and other reports showed that decursin increased caspase-8-mediated apoptosis by increasing TRAIL sensitivity." (PMID 30155480, 2018). "DHAP-induced apoptosis in multiple myeloma cells was detected by Annexin V staining and TUNEL staining (DNA fragmentation), and further confirmed by the activation of caspase-3, caspase-8, and caspase-9, and PARP cleavage." (PMID 28696369, 2017). "Multiple myeloma was sensitive to BTZ, so that anti-cancer therapy using BTZ induces direct tumor cell apoptosis by activating Caspase-8/9 mediated apoptotic pathways." (PMID 28032590, 2017). "An examination of the relative expression levels of FADD, caspase-8, RIP1, and RIP3 in the lenalidomide- and bortezomib-resistant myeloma cells and their parental myeloma cells might help identify a possible programmed cell death pathway to overcome drug resistance." (PMID 35321428, 2022). "The relatively high level of expression of caspase-8 in lenalidomide-resistant RPMI-8226 cells suggested that the expression of caspase-8 might affect lenalidomide sensitivity in myeloma cells; however, this hypothesis has not been investigated yet." (PMID 35321428, 2022). "Interestingly, CASP-8 activation by TRAIL and Btz also leads to CRBN cleavage in myeloma cells." (PMID 33392195, 2020). "Similar findings were reported for multiple myeloma cells where IFN-β induced apoptosis by TRAIL expression, which in turn signaled via an autocrine/ paracrine feedback loop through its receptors DR5 (or DR4) concomitant with recruitment of caspase-8 to the plasma membrane and subsequent cleavage." (PMID 26863029, 2016). "However, the role of caspase-8-dependent downregulation of BimEL during PBOX-15-induced apoptosis of NCI-H929 cells is unclear, and a potential role for cleaved Bim in the amplification of PBOX-15-induced apoptosis in myeloma cells warrants further investigation." (PMID 21179037, 2011).
colitis (24 papers, 2012 to 2025). Inflammation of the colon. "Deficiencies in FADD or caspase-8 have been found to facilitate colitis development via MLKL-mediated necroptosis in epithelial cells." (PMID 38542202, 2024). "From these factors, RNA expression of Bax, Hdac4, IL-18, Casp8 and Hif1 returned to baseline level compared to the colitis- associated upregulation, when MMs were depleted with l-clodronate during DSS-treatment." (PMID 38105266, 2023). "The expression of Hdac4, IL-18 and Casp8 showed a trend similar to Bax’s, where colitis-associated overexpression was diminished in the case of concurrent l-clodronate administration." (PMID 38105266, 2023). "Mice with IEC-specific FADD or caspase-8 deficiency develop colitis depending on MLKL-mediated epithelial cell necroptosis." (PMID 33050394, 2020). "We next evaluated whether the failure of Casp8–/–Ripk3–/– mice to resolve an intestinal C. rodentium infection was associated with altered colitis severity at 14 dpi." (PMID 37080966, 2023). "In mouse models with IEC-specific deficiencies, caspase-8 deficiency (Casp8fl/fl × Vil1-cre, Casp8IEC-KO) has been reported to develop ileitis, as well as impaired mucosal barrier function and bacterial clearance at the epithelial interface, which leads to colitis." (PMID 38542202, 2024). "Inhibition of NLRP3 or Caspase-8 activity ameliorated colitis, with reduction in NLRP3 inflammasome activation, cell death markers, activated T-cells and macrophages, improved histology, and increased abundance of Clostridium cluster XIVa species." (PMID 36656595, 2023). "Moreover, DSS-treated mice administered concurrently with l-clodronate show milder clinical symptoms of colitis, intestinal transit times similar to control animals, and decreased expression of factors implicated in neural inflammation and death, including Bax, Hdac4, IL-18, Casp8 and Hif1a." (PMID 38105266, 2023). "The ileal enteropathy associated with IEC knockout of NEMO, FADD, or CASP8 is TNFR1 independent, even though colitis in those mice is TNFR1 dependent." (PMID 35077396, 2022). "For example, tryptophan treatment attenuates the symptoms and severity of DSS-induced colitis and reduces gut permeability, expression of pro-inflammatory cytokines, and increases expression of the apoptosis initiators caspase-8 and Bax." (PMID 32650570, 2020). "BMSC-EVs also suppressed the apoptosis via reducing the cleavage of caspase-3, caspase-8 and caspase-9 in colitis rats." (PMID 26469068, 2015). "In contrast, caspase-8-deficient mice in the intestinal epithelium develop spontaneous ileitis (and depending on the microbial flora also colitis) and exhibit a lack of PCs and dysregulated antimicrobial functions." (PMID 39461590, 2024). "The initial demonstration of the involvement of necroptosis in the development of intestinal inflammation is based on findings indicating that the removal of either caspase-8 or Fadd in IECs is sufficient to induce necroptosis, leading to spontaneous ileitis and/or colitis." (PMID 39461590, 2024). "Previous studies have shown that epithelial deletion of Caspase-8 promoted DSS-induced colitis." (PMID 36656595, 2023). "Another study has reported that bone mesenchymal stem cells (BMSCs) derived exosome could suppress the apoptosis via reducing the cleavage of caspase-3, caspase-8, and caspase-9 directly in colitis rats." (PMID 31534118, 2019). "This study demonstrates the existence of an abnormal TMEM219-mediated ISC death in CD, which exacerbates colitis, limits ISC-dependent mucosal repair, and acts by activating the Caspase-8 signaling." (PMID 40371646, 2025). "This may provide an explanation for why mice deficient in caspase-8 bear ileitis but no colitis." (PMID 39840043, 2024). "In the same way, celastrol administration has been found to relieve the severity of colitis by decreasing IL-1β, IL-6, myeloperoxidase (MPO), RIPK3, and MLKL levels while increasing active caspase-8 levels and E-cadherin." (PMID 39118979, 2024).
colitis (continued). "Next, we investigated the effects of the small-molecule inhibitors targeting NLRP3 (MCC950) and Caspase-8 (Z-IETD-FMK) on bacterial composition in fecal samples collected on day 0 and 12 from IL10−/− mice with colitis induced by AIEC/piroxicam." (PMID 36656595, 2023). "We show that AIEC and NSAIDs combine to induce/exacerbate colitis and cell death via the NLRP3 inflammasome and Caspase-8 with evidence of NLRP3-Caspase-8 cross-talk contributing to this overall phenotype." (PMID 36656595, 2023). "The colitis in mice with conditional IEC knockout of NEMO, FADD, CASP8, and RIPK1 mice is largely reversed by TNF or TNFR1 deletion." (PMID 35077396, 2022). "Coinciding with the data obtained from the current work, DSS administration was reported an increase caspase-8 levels, which, consequently, enhances TNF-α induced an epithelial necroptosis and promotes the development of colitis." (PMID 35631426, 2022). "ZBP1-driven necroptosis contributes to the death of Casp8−/−Ripk1−/− mice at birth, and TNFR1 and ZBP1 contribute to ileitis and colitis in mice lacking caspase-8 in intestinal epithelial cells." (PMID 38548850, 2024). "Mice lacking intestinal epithelial cell (IEC) caspase-8 develop colitis and ileitis which can be rescued by deletion of MLKL." (PMID 35563804, 2022). "This is a point of high interest, since an involvement of non-canonical caspase-8- and caspase-11-dependent inflammasome activation in the onset and progression of demyielinization and bowel inflammation, respectively, has been documented only in the setting of experimental MS and colitis." (PMID 31200447, 2019). "Colitis and ileitis also occur in mice lacking FADD in IECs, with cell death mediated by MLKL and caspase-8-dependent activation of GSDMD." (PMID 35563804, 2022). "In addition, further studies are needed to evaluate the effects of in vivo selective blockade of non-canonical caspase-8- and caspase-11-dependent NLRP3 activation in animal models of colitis." (PMID 30559669, 2018). "Thus, IEC lacking caspase-8 or FADD due to epithelial cell-specific deletion underwent RIPK3-dependent necroptosis instead of apoptosis in response to TLR or TNF stimulation, leading to a complete absence of Paneth cell, serious tissue damage, enteritis and severe erosive colitis in vivo." (PMID 39840043, 2024).
liver cancer (20 papers, 2007 to 2025). An epithelial or non-epithelial malignant neoplasm that arises from the liver. "A risk model based on the ICD-related genes PRNP, DNM1L, and CASP8 was developed to predict the prognosis of liver cancer." (PMID 37361216, 2023). "To further understand the mechanism by which Ad.SPDD-HCCS1 caused apoptosis of liver cancer cells, we evaluated the key apoptosis-related proteins caspase-3, caspase-8 and caspase-9." (PMID 22040050, 2011). "With the increasing relevance of immunotherapy in treating liver cancer, we focused on assessing the impact of CASP8 on the efficacy of such treatments." (PMID 38186679, 2023). "On the contrary, the down-regulation and low-activity of CASP8 had been reported in various solid organ tumors including liver cancer, small cell lung cancer, gastric adenocarcinoma, and brain tumors." (PMID 35928267, 2022). "As a result, our findings suggest that the antitumor effect of these CMC-Ag nanoparticles is due to the induction of apoptosis and necrosis in hepatic cancer cells via increased caspase-8 and -9 activities and diminished levels of VEGFR-2." (PMID 36015608, 2022). "Genes with 5-mC and 5-hmC level changes enriched in these pathways, such as BMP4, HSP90AA1, DAPK3, FADD and CASP8, have been already reported as potential epigenetic biomarkers for liver cancer." (PMID 31337442, 2019). "Furthermore, the anticancer impact of CMC-AgNPs is due to the induction of apoptosis and necrosis in hepatic cancer cells by increasing caspase-8 and -9 activity and decreasing VEGFR-2." (PMID 36015608, 2022). "CASP8 was identified as the core gene in predicting the prognosis of patients with liver cancer." (PMID 36324154, 2022). "The protein expression levels of CD95, caspase-8, caspase-3 and PARP1 in the tumor tissues and the corresponding normal tissues of 40 liver cancer samples were assessed by western blot analysis." (PMID 25543761, 2015). "Moreover, it has been shown that CAND1 correlates with poor OS in liver cancer, in which silencing CAND1 suppresses the proliferation of liver cancer by inducing caspase-8/RIP1-dependent apoptosis." (PMID 36292029, 2022). "The present study revealed that the expression of caspase-8 was lower in the liver cancer tissues compared with the normal liver tissues." (PMID 25543761, 2015). "Interestingly, the cleavage of caspase-8 was not obvious, suggesting that ginsenoside Rg3 does not activate caspase-8 to induce apoptosis through the death receptor pathway in liver cancer cells." (PMID 35600861, 2022).
diabetes (19 papers, 2007 to 2025). "The CASP8 gene affects the risk of obesity and diabetes in mice by regulating whole-body glucose metabolism." (PMID 36104777, 2022). "Initiation of the extrinsic cascade of apoptosis involving the TNF-α binding with its receptor TNF-R1 as well as dysregulation of the Fas/Fas ligand system caused activation of caspase-8 which favors apoptotic cell loss in diabetes." (PMID 30804780, 2019). "This aligns with a previous report which showed that caspase-8 expression is increased in adipocytes from humans with obesity and diabetes and blockade of caspase-8 prevented weight gain in mice." (PMID 37686623, 2023). "CASP8 can be used as a potential marker for AMI high-risk prediction, and hyperglycemia-related CASP3 predicts diabetes and coronary artery disease events." (PMID 35757636, 2022). "MARCKS-PD ablated caspase 3 and caspase 8 cleavage in embryos exposed to diabetes and reduced the number of apoptotic neuroepithelial cells in embryos from diabetic dams compared to that in embryos from nondiabetic dams." (PMID 30655546, 2019). "Cleaved products for both caspase 8 and caspase 3 were found by western blot analysis in the retinal lysates of rats after two weeks of diabetes, proving the activation of these caspases in the diabetic retina in the rat." (PMID 19641635, 2009). "The protein levels of BCL-2, caspase-9, and caspase-8 were also assessed to examine whether diabetes induces apoptosis in the cochlea." (PMID 34445504, 2021). "Ang (1‐7) downregulates diabetes‐induced iNOS, caspase family members like cleaved caspase 3, cleaved caspase 8 and cleaved caspase 9 as well as Bax expression in the rat pancreas, which are key genes involved in cellular stress and apoptosis, aggravating diabetes progression." (PMID 34561952, 2021). "Recently, increased CASP8 plasma concentration was shown to be a candidate biomarker for diabetes mellitus (DM) because it enhances β-cell apoptosis, leading to both circadian rhythm disruption and DM incidence." (PMID 31450613, 2019). "The significant inhibition of the diabetes-induced activation of caspase 8 and 3 in our model leads to the conclusion that TNF-α induces retinal cell death in diabetes through these two caspases." (PMID 19641635, 2009). "Furthermore, 30 days of exercise has been shown to reduce levels of endoplasmic reticulum stress (ERS) markers, including caspase 12, caspase 8, and C/EBP Homologous Protein (CHOP) in animal models of diabetes, thereby improving liver health." (PMID 39897895, 2025). "Blocking multiple TNFR molecules increases diabetes protection, for example, by overexpression in islets of dominant negative FADD, the adaptor protein used by multiple death receptors to recruit and activate caspase-8." (PMID 17254331, 2007). "In this regard, our result determined that in diabetes conditions, there was an increased level of CHOP in parallel with increased GRP78 that mediated apoptosis by caspase 8, 12, which means high levels of GRP78 could not improve lipid metabolism in diabetic animals." (PMID 38468961, 2024).